CASK (calcium/calmodulin dependent serine protein kinase)
Diseases named in the same sentence as CASK in open-access papers (continued):
Sharing a sentence is not in itself a finding about the gene and the disease.
autism (5 papers, 2020 to 2025). Persistent deficits in social interaction and communication and interaction as well as a markedly restricted repertoire of activity and interest as well as repetitive patterns of behavior. "CASK is part of a signaling pathway that includes the widely validated autism susceptibility gene CNTNAP2 and the Prader Willi syndrome gene NECDIN." (PMID 38978588, 2024). "Our study implicates three ASD-susceptible genes, CNTNAP2, Necdin and CASK, may participate in the autism-related behaviors through a common pathway." (PMID 37271769, 2023).
colorectal cancer (5 papers, 2016 to 2024). A primary or metastatic malignant neoplasm that affects the colon or rectum. "Moreover, there is an association between high expression of CASK and unfavorable prognosis of colorectal cancer." (PMID 33113509, 2020). "A recent study showed that co-upregulation of CASK and syndecan-2 in colorectal cancer is associated with an unfavorable prognosis, suggesting that CASK could be a prognostic factor for colorectal cancer metastasis." (PMID 26869927, 2016). "We aimed to investigate the different effects between CASK promoter methylation heterogeneity and homogeneity on colorectal cancer (CRC) patients' prognosis." (PMID 33113509, 2020). "The role of CASK in carcinoma has been reported only in oesophageal cancer, gastric cancer and colorectal cancer." (PMID 32336950, 2020). "Specifically, the short MADD-4 isoform (MADD-4B) activates UNC-40/DCC (deleted in colorectal cancer) signaling, recruiting an intracellular postsynaptic scaffold composed of FRM-3, a FERM domain protein, and LIN-2/CASK." (PMID 39190555, 2024).
FG syndrome 4 (5 papers, 2013 to 2025). Any FG syndrome in which the cause of the disease is a mutation in the CASK gene. "In humans, the CASK gene is X-linked and its mutation leads to FG syndrome 4, a form of X-linked mental retardation." (PMID 38978588, 2024).
hepatocellular carcinoma (5 papers, 2020 to 2025). A malignant tumor that arises from hepatocytes. "Based on these findings, a potential miR-497-mRNA or miR-1246-mRNA regulatory network can be established, namely, miR-497-ARL2/UBE2Q1/PHF19/APLN/CHEK1/CASK/SUCO/CCNE1/KIF23, or miR-1246-AUTS2/SLAIN1, which contributes to the occurrence and development of hepatocellular carcinoma." (PMID 34163524, 2021). "Interestingly, when we studied the TCGA database by using the GEPIA web tool, we also found that patients with high CASK expression tended to have poorer OS and RFS than other hepatocellular carcinoma patients." (PMID 32336950, 2020). "CASK and AUTS2 genes have not yet been reported on the mechanism of their involvement in hepatocellular carcinoma." (PMID 34163524, 2021).
Ataxia (4 papers, 2016 to 2025). Ataxia refers to impaired coordination of voluntary muscle movement. "CASK+/- HprteGFP/+ mice exhibited clasping and crossing of their limbs and were immobilized indicating they have cerebellar ataxia." (PMID 40422253, 2025). "CASK heterozygous knockout female mice (CASK(+/−)) phenocopy the human motor limitations with high fidelity showing motor incoordination and ataxia." (PMID 29258560, 2017). "CASK(+/-) mice fall off a rotarod much earlier (<2 min) than control mice (~6 min) due to ataxia in the first two days of training." (PMID 27036546, 2016). "Surprisingly, we also found that CASK(+/-) mice expend significantly more energy at rest, which is likely attributable to ataxia and imbalance in these mice." (PMID 27036546, 2016).
breast carcinoma (4 papers, 2012 to 2025). "For examples in Breast Cancer, CASK (calcium/calmodulin-dependent serine protein kinase) and CIT (rho-interacting, serine/threonine kinase 21) are ranked 161 and 115, and with a 2.88 and 3.06 fold change in gene expression of breast cancer tissues, respectively." (PMID 22952662, 2012).
Epileptic encephalopathy (4 papers, 2015 to 2022). A condition in which epileptiform abnormalities are believed to contribute to the progressive disturbance in cerebral function. "Loss‐of‐function mutations in the X‐linked gene CASK are frequently lethal in males or produce epileptic encephalopathy with severe neurodevastation." (PMID 32696595, 2020). "Although haploinsufficiency of CASK gene in females might present with seizures with incomplete penetrance (~40%) (Moog, Uyanik, & Kutsche, 1993), hemizygous CASK mutations in males produces catastrophic neurodevastation and epileptic encephalopathy." (PMID 32696595, 2020).
pontocerebellar hypoplasia (4 papers, 2012 to 2025). Pontocerebellar hypoplasias (PCH) are a rare heterogeneous group of diseases characterized by hypoplasia and atrophy and/or early neurodegeneration of the cerebellum and pons. "Thus, the brain imaging findings are the major diagnostic clue and should prompt CASK testing, however, the differential diagnosis of other pontocerebellar hypoplasia (PCH) forms can be challenging." (PMID 25886057, 2015). "This study describes a new series of PCH female patients with CASK inactivating mutations and confirms that these patients have a recognizable although variable phenotype consisting of a specific form of pontocerebellar hypoplasia." (PMID 22452838, 2012).
prostate carcinoma (4 papers, 2014 to 2025). A carcinoma that arises from epithelial cells of the prostate gland. "Although this claim awaited further validation on larger sizes of samples, CASK dysregulated levels might prove valuable as prognostic markers, especially as CASK overexpression seemed to be strongly associated with the poor prognosis in both metastatic breast and prostate cancers." (PMID 25373785, 2014).
autism spectrum disorder (3 papers, 2014 to 2023). A spectrum of developmental disorders that includes autism, and Asperger syndrome. "Neurexin, Neuroligin, and CASK mutations are all linked to Autism Spectrum Disorders (ASD)." (PMID 26575289, 2015). "We applied a battery of bioinformatics algorithms designed to predict potential impact on protein structure to five pathogenic missense mutations in the protein CASK that have been shown to underlie pathologies ranging from X-linked mental retardation to autism spectrum disorder." (PMID 24505460, 2014).
focal segmental glomerulosclerosis (3 papers, 2019 to 2025). A renal disorder characterized by sclerotic lesions in the glomeruli. "Circulating CASK has also been associated with post-transplantation recurrence of focal segmental glomerulosclerosis (FSGS)." (PMID 33535372, 2021).
Lissencephaly (3 papers, 2015 to 2022). A spectrum of malformations of cortical development caused by insufficient neuronal migration that subsumes the terms agyria, pachygyria and subcortical band heterotopia. "In contrast to lissencephaly, the CASK(+/-) cerebellum exhibited normal layering of cells." (PMID 27036546, 2016).
optic atrophy (3 papers, 2012 to 2024). A disorder characterized by loss of optic nerve fibers. "The two male patients with MICPCH and non mosaic CASK mutations presented with a severe PCH, severe neurological impairment with near absent development, absence of sucking and swallowing, optic atrophy, refractory epilepsy and edema of the hands and feet in one." (PMID 22452838, 2012).
schizophrenia (3 papers, 2014 to 2023). A major psychotic disorder characterized by abnormalities in the perception or expression of reality. "All these genes are associated with psychiatric conditions, ranging from ID i.e., CNKSR2, CTNNB1, ANK3, CASK and ASD i.e., CTNND2, ANK3 to schizophrenia i.e., CNKSR2 (GWAS, PGC-SCZ 2014) and bipolar disorder ANK3." (PMID 28713243, 2017).
Cerebellar atrophy (2 papers, 2012 to 2022). Cerebellar atrophy is defined as a cerebellum with initially normal structures, in a posterior fossa with normal size, which displays enlarged fissures (interfolial spaces) in comparison to the foliae secondary to loss of tissue. "This phenotype is reminiscent of PEHO syndrome but the presence of severe PCH unlike progressive cerebellar atrophy should prompt to look for CASK mutations." (PMID 22452838, 2012). "Interestingly, the loss of balance does not occur until cerebellar atrophy is present, indicating that the observed ataxia results from damage to the tissue rather than loss of CASK molecular function." (PMID 35406695, 2022).
cognitive deficits (2 papers, 2013 to 2023). "Flies homozygous for a hypomorphic CASK mutation (∆18) have motor and cognitive deficits." (PMID 37805506, 2023). "Therefore, the finding that CASK can regulate CaMKII autophosphorylation suggests that this mechanism may have a role in the cognitive deficits induced by CASK mutation in humans." (PMID 24062638, 2013).
hypomyelinating leukodystrophy-14 (2 papers, 2021 to 2025). "This included hypomyelinating leukodystrophy-14, NBIA/PKAN, CASK-related disorders, presumed PANK2 mutations (6 cases), and other idiopathic focal dystonia that spread out to paraspinal muscles (1 case)." (PMID 40864051, 2025).
infantile spasms (2 papers, 2023). A rare epilepsy syndrome characterized by onset of epileptic spasms in infants between 2 and 12 months of age, and rarely up to 24 months. "Mutations or deletions in the CASK gene have been discovered in patients with neurodevelopmental disorders, including X-linked intellectual disability (XLID), autism, infantile spasms, nystagmus, optic atrophy, and FG syndrome." (PMID 37190086, 2023).
Joubert syndrome (2 papers, 2019 to 2024). Joubert syndrome (JS) is characterized by congenital malformation of the brainstem and agenesis or hypoplasia of the cerebellar vermis leading to an abnormal respiratory pattern, nystagmus, hypotonia, ataxia, and delay in achieving motor milestones. "In the infantile‐onset group, the most common underlying disease was Joubert syndrome and related disorders (n = 11), followed by SCA29 (n = 4), mitochondrial diseases (n = 4), and CASK‐related disorders (n = 4)." (PMID 31469254, 2019).
mental disorder (2 papers, 2022 to 2024). A disease that has its basis in the disruption of mental process. "The pathogenic variation of CASK gene can cause CASK related mental disorders." (PMID 35550617, 2022). "The pathogenic variants can lead to CASK related mental disorders." (PMID 35550617, 2022).
pancreatic cancer (2 papers, 2025). "It has been shown that the polarity protein CASK is significantly upregulated in pancreatic cancer tissues, and silencing of CASK can attenuate the unrestricted proliferation of tumour cells by inhibiting the Notch pathway in pancreatic cancer cells." (PMID 40801824, 2025).
Parkinson disease (2 papers, 2014 to 2024). A progressive degenerative disorder of the central nervous system characterized by loss of dopamine producing neurons in the substantia nigra and the presence of Lewy bodies in the substantia nigra and locus coeruleus. "In particular, CASK appears to associate with a number of mitochondrial proteins, including DJ-1(dj-1β), a mitochondrial stability factor involved in Parkinson's disease." (PMID 25071438, 2014).
scoliosis (2 papers, 2016 to 2020). A congenital or acquired spinal deformity characterized by lateral curvature of the spine. "Similar to CASK patients, CASK(+/-) mice display scoliosis with a high degree of penetrance (~85 %)." (PMID 27036546, 2016).
Seizure (2 papers, 2023). A seizure is an intermittent abnormality of nervous system physiology characterized by a transient occurrence of signs and/or symptoms due to abnormal excessive or synchronous neuronal activity in the brain. "Fifteen missense mutations have been identified in association with epileptic seizures, and the locations of these mutations do not converge on specific domains but diverge over all the functional domains of the CASK protein." (PMID 37628707, 2023).
Athetosis (1 paper, 2025). A slow, continuous, involuntary writhing movement that prevents maintenance of a stable posture. "Progressive dystonia was associated with ANO3 and a microdeletion in Xp11.4 including the CASK gene, whereas progressive athetosis was seen with ATM and TWNK." (PMID 40326640, 2025).
Atrophy (1 paper, 2025). Any weakening or degeneration, especially through lack of use. "Interestingly, the cerebellar atrophy was more severe in female heterozygous mice, which had a mixture of cells with normal CASK expression and cells with reduced CASK expression, than in male hemizygous mice, which had reduced CASK expression in all cerebellar cells." (PMID 40422238, 2025).
Cerebral atrophy (1 paper, 2020). Atrophy (wasting, decrease in size of cells or tissue) affecting the cerebrum. "Strikingly, in both reported cases of CASK R27* mutation in males, a progressive cerebral atrophy has been noted." (PMID 32696595, 2020).
CNS leukemia (1 paper, 2020). "CASK and AFDN have also been implicated in CNS diseases such intellectual disabilities and CNS leukemia, respectively." (PMID 32984858, 2020).
colitis (1 paper, 2015). Inflammation of the colon. "P2X3 mRNA and protein expression in the colon and dorsal root ganglia were similar in control, acute colitis and post-colitis groups, while colonic mRNA expression of cdk5, csk and CASK was increased in the post-colitis group only." (PMID 25885345, 2015). "To investigate their involvement, we performed RT-PCR for Cdk5, Csk and CASK mRNA expression in the colon and DRGs (Th13-L2 and L6-S1) of control, acute colitis and post-colitis rats." (PMID 25885345, 2015).
colon cancer (1 paper, 2015). "Of particular interest, three additional PDZ proteins—DLG1, CASK, and LIN7A—were detected in SW480 colon cancer cells, suggesting additional, yet to be characterized, ADRA1D complexes exist and are cell-type dependent." (PMID 26617989, 2015).
colorectal tumor (1 paper, 2021). "Previous studies demonstrated that CASK is up-regulated in various tumors including, colorectal tumor, esophageal cancer, indicating that it might promote their progression or metastasis." (PMID 33969375, 2021).
congenital nystagmus (1 paper, 2011). Nystagmus present at birth or caused by lesions sustained in utero or at the time of birth. "Three novel missense mutations and one splice site mutation of CASK were found in 4 families with mild to moderate X-linked mental retardation and congenital nystagmus." (PMID 21569638, 2011). "Thus the phenotypes associated with CASK mutations range from mild MR with or without congenital nystagmus, to severe cognitive impairment associated with cerebellar and pontine hypoplasia and abormalities of cortical development." (PMID 21569638, 2011).
diabetic nephropathy (1 paper, 2019). "We did not detect CASK in the sera from patients with significant proteinuria (>3 g/day) in diabetic nephropathy or caused by membranous nephropathy, and minimal change disease, or in healthy individuals." (PMID 31356645, 2019).
Duchenne/Becker muscular dystrophy (1 paper, 2023). "As with Duchenne/Becker muscular dystrophy, one initial strategy would be to convert a severe CASK phenotype to a mild one." (PMID 37805506, 2023).
Epileptic spasm (1 paper, 2016). A sudden flexion, extension, or mixed extension-flexion of predominantly proximal and truncal muscles that is usually more sustained than a myoclonic movement but not as sustained as a tonic seizure. "Incidentally, epileptic spasms and epileptic disorders have been demonstrated in patients with CASK mutations." (PMID 27036546, 2016).
eye movement disorders (1 paper, 2012). "CASK is a candidate gene for X-linked mental retardation and eye movement disorders." (PMID 23008758, 2012).
familial hemiplegic migraine type 1 (1 paper, 2013). "The present study investigated the role of calcium/calmodulin-dependent serine protein kinase (CASK) in controlling P2X3 receptor expression and function in trigeminal ganglia from Cacna1a R192Q-mutated knock-in (KI) mice, a genetic model for familial hemiplegic migraine type-1." (PMID 24294842, 2013).
heart failure (1 paper, 2025). Inability of the heart to pump blood at an adequate rate to meet tissue metabolic requirements. "Furthermore, CASK knockout induces heart failure via CaMKII activation, highlighting the critical roles of calmodulin‐related genes in cardiac function." (PMID 40078074, 2025).
Hypercholesterolemia (1 paper, 2018). An increased concentration of cholesterol in the blood. "Although cardiac ADRB2 and CNB1 were significantly downregulated by hypercholesterolemia, the expression of CASK was not altered by hypercholesterolemia." (PMID 29973623, 2018).
keloid (1 paper, 2019). An irregularly shaped, elevated mark on the skin caused by deposits of excessive amounts of collagen during wound healing. "Additionally, the mechanism of ART inhibited the proliferation of fibroblast in keloid may be related to the up-regulation of calcium/calmodulin-dependent serine protein kinase (CASK) and down-regulation of inhibitors of differentiation 1(ID1)." (PMID 31396694, 2019).
learning disabilities (1 paper, 2023). "In addition, NM_003688.3(CASK):c.172 + 1G > A was inherited from the asymptomatic mother, found at the hemizygous state in one symptomatic uncle with learning disabilities and absent from another asymptomatic uncle." (PMID 36765386, 2023).
memory impairment (1 paper, 2013). "Bidirectional changes in CASK expression in the γ neurons led to memory impairments, indicating that the correct level of CASK in the mushroom body is required for memory formation." (PMID 24062638, 2013).
migraine (1 paper, 2021). "We for the first time show that the genetic interaction and synergetic effect between variants in NRXN2, GABRE and CASK, affects migraine predisposition." (PMID 34126933, 2021). "This study unravels, for the first time, the gene-gene interactions between NRXN2, GABRE - a GABAA-receptor - and CASK, importantly it shows the synergetic effect between those genes and its relation with migraine susceptibility." (PMID 34126933, 2021). "Likewise, we also verified the evidence for genetic interaction between NRXN2 and CASK in migraine susceptibility." (PMID 34126933, 2021). "Therefore, we aimed to further investigate the role and interaction of NRXN2, SYT1, GABRE and CASK, additional components involved in the control mechanisms of neurotransmitter release apparatus in migraine susceptibility." (PMID 34126933, 2021). "Previously, we have provided data evidencing the role of CASK in the pathophysiology of migraine, reinforcing the role of calcium homeostasis in this neurological disorder." (PMID 34126933, 2021).
neurodevelopmental disability (1 paper, 2020). "In conclusion, with early clinical management and palliative interventions that assist with respiration and nutrient delivery, subjects born without functional CASK protein may develop beyond infancy, albeit with profound neurodevelopmental disability." (PMID 32696595, 2020).
osteosarcoma (1 paper, 2026). A usually aggressive malignant bone-forming mesenchymal neoplasm, predominantly affecting adolescents and young adults. "Inhibiting the expression of CASK can significantly promote cell apoptosis and inhibit the cycle progression of osteosarcoma cells." (PMID 41919243, 2026).
panic disorder (1 paper, 2018). An anxiety disorder characterized by multiple unexpected panic attacks with persistent concern of recurring attacks. "Interestingly, PSD-95 and the CASK complex bind to the 5-hydroxytryptamine type 2A serotonin receptor (5-HT2A), which is involved in panic disorders, and PSD-95 mutants exhibit panic-like behavior in a behavioral test battery." (PMID 30359304, 2018).
rectal cancer (1 paper, 2020). A primary or metastatic malignant neoplasm that affects the rectum. "According to the result of the subgroup analysis, we observed that the disadvantageous effect of CASK homogeneous methylation on survival was still significant among older (≥ 50), Dukes staging C/D, and rectal cancer patients." (PMID 33113509, 2020).